LHPP (phospholysine phosphohistidine inorganic pyrophosphate phosphatase)
Diseases named in the same sentence as LHPP in open-access papers (continued):
Sharing a sentence is not in itself a finding about the gene and the disease.
colorectal cancer (8 papers, 2021 to 2025). A primary or metastatic malignant neoplasm that affects the colon or rectum. "Studies have shown that LHPP overexpression impeded colorectal cancer cell growth and proliferation in vitro, and was associated with a change in PI3K/AKT activity." (PMID 34926462, 2021). "Importantly, the expression of LHPP protein was shown to correlate with survival of patients suffering from colorectal cancer (CRC), a type of cancer that is often linked to chronic inflammation." (PMID 37626656, 2023). "In colorectal cancer, LHPP inhibits the migration and invasion of cancer cells by suppressing the phosphorylation of Smad3 in the TGF-β pathway." (PMID 40240758, 2025). "Most recently, the TGF‐β/Smad signaling pathway was considered a signaling pathway LHPP participated in to regulate cell migration and invasion in colorectal cancer and intrahepatic cholangiocarcinoma." (PMID 38292328, 2024). "In a previous study, LHPP expression was significantly lower in colorectal cancer tissues and inversely correlated to tumor severity and worse overall survival." (PMID 34608127, 2021). "Our previous study also demonstrated that LHPP could repress the proliferation and progression of colorectal cancer cells by inhibiting PI3K/AKT pathway." (PMID 36376886, 2022). "LHPP could inhibit colorectal cancer cell proliferation and growth by inactivating the PI3K/AKT signaling pathway." (PMID 34608127, 2021). "In addition, our team suggested that LHPP protein might impede the metastasis of colorectal cancer by mediating the phosphorylation of Smad3 in TGF-β/Smad canonical pathway." (PMID 36376886, 2022). "However, the functions and potential mechanisms of LHPP as a tumor suppressor in colorectal cancer (CRC) metastasis are still unknown." (PMID 34608127, 2021). "When CRC cells treated with SIS3, LHPP could not play its role in the progression of colorectal cancer." (PMID 34608127, 2021).
cervical carcinoma (6 papers, 2020 to 2024). A carcinoma arising from either the exocervical squamous epithelium or the endocervical glandular epithelium. "According to existing researches, LHPP is capable of inhibiting cervical carcinoma cells from the proliferation and metastasis, as well as facilitating their apoptosis by AKT regulation." (PMID 35002505, 2022). "Silencing LHPP in cervical cancer promotes cell metastasis, apoptosis and proliferation through AKT." (PMID 33418541, 2021). "In cervical cancer, it is also found that LHPP can promote apoptosis by increasing the expression of cleaved-PARP and cleaved-Casp3 protein." (PMID 32186702, 2020). "In addition, over‐expressing LHPP suppressed cervical cancer cell proliferation and metastasis." (PMID 31693242, 2020). "LHPP is a histidine phosphatase and reported to function as the tumor suppressor role in HCC and cervical cancer, and it modulated tumor progression by inhibiting AKT phosphorylation." (PMID 33121495, 2020).
bladder cancer (5 papers, 2020 to 2025). "Complying with this finding in bladder carcinoma, LHPP down-regulation can enhance cell viability and colony formation through AKT/p65 pathway." (PMID 35002505, 2022). "LHPP reduction promoted bladder cancer cell proliferation and growth by mediating the AKT/p65 signaling pathway." (PMID 34608127, 2021). "As a new tumor suppressor, the anti-tumor effect of LHPP in melanoma and bladder cancer has been further confirmed." (PMID 32186702, 2020). "Here, we found that LHPP expression decreased in PaCa tissues and cells, indicating that LHPP was a potential tumor suppressor, which is consistent with the findings in melanoma and liver, cervical, and bladder cancers." (PMID 32186702, 2020). "In bladder cancer, LHPP inhibits cell growth in vitro and in vivo via regulating the AKT/p65 signaling pathway." (PMID 33426063, 2020).
depression (5 papers, 2016 to 2023). "Another study including 12 000 Han Chinese women revealed 2 genes (SIRT1 and LHPP) to be significantly associated with severe depressive disorder." (PMID 38012695, 2023). "Based on the large number of samples studied on LHPP rs35936514 associated with MDD in Chinese subjects, it was here noted that LHPP was associated with thyroid disorders, which may affect depression." (PMID 27843651, 2016).
melanoma (5 papers, 2020 to 2025). A malignant, usually aggressive tumor composed of atypical, neoplastic melanocytes. "Both the protein and mRNA levels of LHPP were clearly reduced in most melanoma cell lines." (PMID 40988976, 2025). "In melanoma, overexpression of LHPP inhibits cell proliferation in vitro and in vivo." (PMID 33426063, 2020).
pancreatic cancer (5 papers, 2020 to 2024). "In HCC and pancreatic cancer, LHPP binds to the epidermal growth factor receptor (EGFR) and inhibits its phosphorylation, negatively regulating the activation of downstream pathways, including ERK, AKT, and STAT3, leading to decreased metastatic potential." (PMID 39063217, 2024). "As indicated from existing reports, the protein histidine phosphatase LHPP acts as a vital factor in tumorigenesis in liver, lung, bladder, breast and pancreatic tumor tissues." (PMID 35002505, 2022). "In pancreatic cancer, enhanced LHPP expression restored PTEN protein and repressed the AKT phosphorylation resulted to inhibition of PaCa (Pancreatic cancer) progression and metastasis." (PMID 34608127, 2021). "In pancreatic cancer, LHPP suppresses cell proliferation and metastasis and promotes cell apoptosis via interacting with the PTEN/AKT signaling pathway." (PMID 33426063, 2020). "LHPP expression in pancreatic carcinoma with lymph node metastasis was significantly lower than in that without lymph node metastasis (P = 0.010)." (PMID 32186702, 2020). "In addition, LHPP expression was significantly lower in HPDE6-C7 cells than that in pancreatic cancer cell lines." (PMID 32186702, 2020). "The inhibitory effect of LHPP on the development of pancreatic cancer cells may provide a new theoretical basis for the treatment of PaCa." (PMID 32186702, 2020). "In this experiment, LHPP expression was lower in cancer tissues than that in normal pancreatic tissue, and clinicopathological results showed that LHPP expression was correlated with the degree of differentiation and lymphatic metastasis of pancreatic carcinoma." (PMID 32186702, 2020).
liver cancer (4 papers, 2021 to 2025). An epithelial or non-epithelial malignant neoplasm that arises from the liver. "Subsequent studies found that LHPP expression is reduced in liver cancer tissues, and overexpression of LHPP inhibits the progression and severity of liver cancer in animal models, suggesting its tumor‐suppressive role." (PMID 38292328, 2024). "We could observe that LHPP was significantly expressed in normal liver tissues (Supplement 1A) and widely expressed in cytoplasmic and membrane, while LHPP was weakened in liver cancer tissues (Supplement 1B)." (PMID 35002505, 2022). "LHPP was identified as a protein histidine phosphatase, which may act as a liver cancer suppressor gene." (PMID 33796530, 2021).
alcohol dependence (3 papers, 2022 to 2023). Physical and psychological dependence on alcohol. "Finally, an interaction between a variant in Phospholysine Phosphohistidine Inorganic Pyrophosphate Phosphatase (LHPP) and alcohol dependence moderated self-reported history of risky sexual behavior and was associated with brain circuitries previously implicated in the inhibition of risky behavior." (PMID 37582857, 2023).
glioblastoma (3 papers, 2022 to 2024). The most malignant astrocytic tumor (WHO grade IV). "Furthermore, LHPP is absent in glioblastoma, and it is associated with a poor prognosis." (PMID 39063217, 2024). "Here, overexpression of LHPP could impede glycolysis and respiration by inducing ubiquitin-mediated degradation of PKM2, inhibiting the growth of glioblastoma." (PMID 39063217, 2024). "His research proved that LHPP could regulate the cancer energy metabolic process via impeding glycolysis and respiration through the induction of ubiquitin-mediated degradation of PKM2 in glioblastoma." (PMID 36376886, 2022). "Another study reported that LHPP induced the ubiquitin-mediated degradation of PKM2 in glioblastoma; however, phosphorylated PKM2 was not a direct target of LHPP." (PMID 39063217, 2024).
nasopharyngeal carcinoma (3 papers, 2024 to 2025). A carcinoma arising from the nasopharyngeal epithelium. "For instance, in nasopharyngeal carcinoma, TRIM21-mediated K48-linked ubiquitination promotes the degradation of LHPP and then downregulates TYK2-STAT1phosphorylation to inhibit the progression of nasopharyngeal carcinoma." (PMID 40379610, 2025). "HDAC4 was overexpressed in nasopharyngeal carcinoma (NPC) cells and promoted their proliferation and metastasis by upregulating TYK2-STAT1 phosphorylation through HDAC4/LHPP signal axis." (PMID 38702756, 2024).
cholangiocarcinoma (2 papers, 2022 to 2024). A carcinoma that arises from the intrahepatic biliary tree (intrahepatic cholangiocarcinoma) or from the junction, or adjacent to the junction, of the right and left hepatic ducts (hilar cholangiocarcinoma). "In cholangiocarcinoma and CRC, LHPP inhibits tumorigenesis by suppressing the TGFβ/Smad signaling pathway." (PMID 39063217, 2024).
colitis (2 papers, 2022 to 2023). Inflammation of the colon. "In summary, we show that the loss of LHPP and increased histidine phosphorylation in intestinal epithelial cells correlate with colitis." (PMID 37626656, 2023). "We analyzed histidine phosphorylation in DSS-driven inflamed mouse colon tissue samples and generated LHPP knockout mice to study the effect of the loss of this histidine phosphatase on colitis development and histidine phosphorylation in vivo." (PMID 37626656, 2023). "To determine whether loss of LHPP indeed affects the progression of colitis, we treated Lhpp−/− and Lhpp+/+ littermates with DSS." (PMID 37626656, 2023). "On the basis of our observation that DSS treatment resulted in the loss of LHPP in wild-type mice, we formulated the hypothesis that LHPP plays an essential role during colitis development." (PMID 37626656, 2023). "To obtain insights into the role of LHPP in normal development and in the progression of colitis, we generated full-body LHPP knockout (Lhpp−/−) mice using CRISPR/Cas9." (PMID 37626656, 2023). "The histidine phosphatase LHPP is downregulated in colon samples from Crohn’s disease and ulcerative colitis patients, and from mice with experimentally induced colitis, suggesting the involvement of this protein in IBD." (PMID 37626656, 2023). "After one week of treatment, LHPP expression was further reduced, indicating that LHPP expression was negatively correlated with the severity of colitis." (PMID 37626656, 2023). "Future studies are necessary to evaluate if the reintroduction of LHPP can also prevent or rescue colitis, and whether targeting histidine phosphorylation could be a path forward to develop novel therapeutics in the field of IBD and/or CRC." (PMID 37626656, 2023). "Other colitis-related parameters such as colon shrinkage and elevated spleen weight were also similar in Lhpp−/− and Lhpp+/+ mice, indicating that the loss of LHPP does not impact the development of colitis." (PMID 37626656, 2023). "However, the deletion of LHPP alone was not sufficient to induce inflammation in the colon or to promote the DSS-induced colitis phenotype in mice." (PMID 37626656, 2023).
esophageal cancer (2 papers, 2021 to 2022). A primary or metastatic malignant neoplasm involving the esophagus. "Thus, the biological functions of LHPP in gastrointestinal and esophageal cancers were investigated." (PMID 34608127, 2021).
gastric adenocarcinoma (2 papers, 2022 to 2025). "Additionally, the highest frequency of LHPP genetic alteration (3.86%) was occurred in stomach adenocarcinoma with amplification as the primary alteration type, and the rate of amplification in STAD was 2.50%." (PMID 36376886, 2022).
gastric tumor (2 papers, 2022 to 2024). "We discovered that the expression of LHPP was lower in gastric tumor tissues than in adjacent normal tissues identified by the TCGA database and 90 GC patients’ samples." (PMID 38292328, 2024). "LHPP expression in normal tissues was significantly higher than that in gastric tumour tissues." (PMID 35568711, 2022).
lung carcinoma (2 papers, 2022 to 2024). "In conclusion, the novel construct GD55-LHPP provides a valuable strategy for lung cancer-targeted therapy and develop the role of tumor suppress gene LHPP in lung cancer gene therapy." (PMID 38849383, 2024). "The results showed that LHPP had lower expression in either lung cancer cells or clinical lung cancer tissues compared with normal cells or tissues, and GD55-LHPP effectively mediated LHPP expression in lung cancer cells." (PMID 38849383, 2024). "This includes the NME family of likely histidine kinases, as well as the protein histidine phosphatase LHPP which has multifaceted activity as a tumour suppressor for a range of cancers, and the histidine phosphatase PHPT1, which is an oncogene involved in lung cancer." (PMID 36048825, 2022).
lymph node metastasis (2 papers, 2020). "Subgroup analysis also indicated that LHPP was significantly downregulated in higher stages and lymph node metastasis (pN1 vs. pN0) patients." (PMID 33121495, 2020). "In our experiment, we also found that the degree of PaCa differentiation was negatively correlated with LHPP expression, and LHPP expression in PaCa with lymph node metastasis was significantly lower than in that without lymph node metastasis." (PMID 32186702, 2020).
renal cell carcinoma (2 papers, 2020 to 2024). "In renal cell carcinoma, miR-765, miR-21, and miR-144 can downregulate LHPP expression, promoting EMT, proliferation, and invasion of RCC cells." (PMID 39063217, 2024).
acute lymphoblastic leukemia (1 paper, 2024). Leukemia with an acute onset, characterized by the presence of lymphoblasts in the bone marrow and the peripheral blood. "Subsequently, according to genome‐wide association analysis, LHPP was regarded as a susceptibility loci for pharyngeal cancer and childhood acute lymphoblastic leukemia in 2016 and 2017 successively." (PMID 38292328, 2024).
brain glioma (1 paper, 2022). A malignant glioma that involves the brain. "Especially in brain glioma, the data demonstrated that patients with high LHPP expression have a better prognosis of overall and disease-free survival." (PMID 36376886, 2022).
breast carcinoma (1 paper, 2024). "Patients with high LHPP expression have a better prognosis in CRC in brain glioma, renal carcinoma, HCC, and breast cancer." (PMID 39063217, 2024).
glioma (1 paper, 2022). A benign or malignant brain and spinal cord tumor that arises from glial cells (astrocytes, oligodendrocytes, ependymal cells). "Interestingly, we noticed that brain lower grade glioma patients (LGG) with high LHPP expression had better overall survival and disease-free survival." (PMID 36376886, 2022).
hyperthyroidism (1 paper, 2024). Overactivity of the thyroid gland resulting in overproduction of thyroid hormone and increased metabolic rate. "One study found that LHPP is associated with hyperthyroidism, and overexpression of LHPP in hyperthyroidism may contribute to carcinogenesis in the thyroid." (PMID 39063217, 2024).
lung adenocarcinoma (1 paper, 2022). A carcinoma that arises from the lung and is characterized by the presence of malignant glandular epithelial cells. "In contrast, the LHPP gene had obviously lower expression in lung adenocarcinoma (LUAD) normal tissues than in adjacent cancer tissues." (PMID 36376886, 2022).
Obesity (1 paper, 2025). Accumulation of substantial excess body fat. "Additionally, in the full population, the CpG site cg25114752, annotated to SNORD116-8, and the CpG site cg12320621, annotated to LHPP, were significantly associated with all three obesity indicators." (PMID 40702573, 2025).
osteosarcoma (1 paper, 2024). A usually aggressive malignant bone-forming mesenchymal neoplasm, predominantly affecting adolescents and young adults. "On the other hand, ATP6V0D1 and LHPP were negatively correlated with risk scores, which suggested that they are protective genes for the clinical prognosis of patients with osteosarcoma." (PMID 38506898, 2024). "In this research, five oxidative phosphorylation genes linked to the prognosis of individuals with osteosarcoma were screened out, including ATP6V0D1, LHPP, COX6A2, MTHFD2, and NDUFB9." (PMID 38506898, 2024). "However, the present study has presented novel findings, establishing LHPP as a prognosis-protective gene for osteosarcoma." (PMID 38506898, 2024). "To date, there have been no studies exploring the association of LHPP with osteosarcoma." (PMID 38506898, 2024).
ovarian serous cystadenocarcinoma (1 paper, 2022). A malignant serous cystic epithelial neoplasm arising from the ovary. "The most frequent mutation type in LHPP was amplification, which was mainly observed in ovarian serous cystadenocarcinoma." (PMID 36376886, 2022).
sarcoma (1 paper, 2022). A usually aggressive malignant neoplasm of the soft tissue or bone. "LHPP gene expression levels were definitely reduced in tumor tissues compared with normal tissues among sarcoma (SARC) and testicular germ cell tumors (TGCT)." (PMID 36376886, 2022).
schizophrenia (1 paper, 2022). A major psychotic disorder characterized by abnormalities in the perception or expression of reality. "Additionally, we identified fifty-five common and rare variants that exhibited gene-interaction effects including three variants in the CAMK1D gene and four variants in LHPP; both genes are linked to schizophrenia." (PMID 35342390, 2022).